HSP90AB1 (heat shock protein 90 alpha family class B member 1)
Description:
Molecular chaperone that promotes the maturation, structural maintenance and proper regulation of specific target proteins involved for instance in cell cycle control and signal transduction. Undergoes a functional cycle linked to its ATPase activity. This cycle probably induces conformational changes in the client proteins, thereby causing their activation. Interacts dynamically with various co-chaperones that modulate its substrate recognition, ATPase cycle and chaperone function. Engages with a range of client protein classes via its interaction with various co-chaperone proteins or complexes, that act as adapters, simultaneously able to interact with the specific client and the central chaperone itself. Recruitment of ATP and co-chaperone followed by client protein forms a functional chaperone. After the completion of the chaperoning process, properly folded client protein and co-chaperone leave HSP90 in an ADP-bound partially open conformation and finally, ADP is released from HSP90 which acquires an open conformation for the next cycle. Apart from its chaperone activity, it also plays a role in the regulation of the transcription machinery. HSP90 and its co-chaperones modulate transcription at least at three different levels. They first alter the steady-state levels of certain transcription factors in response to various physiological cues. Second, they modulate the activity of certain epigenetic modifiers, such as histone deacetylases or DNA methyl transferases, and thereby respond to the change in the environment. Third, they participate in the eviction of histones from the promoter region of certain genes and thereby turn on gene expression. Antagonizes STUB1-mediated inhibition of TGF-beta signaling via inhibition of STUB1-mediated SMAD3 ubiquitination and degradation. Promotes cell differentiation by chaperoning BIRC2 and thereby protecting from auto-ubiquitination and degradation by the proteasomal machinery. Main chaperone involved in the phosphorylation/activation of the STAT1 by chaperoning both JAK2 and PRKCE under heat shock and in turn, activates its own transcription. Involved in the translocation into ERGIC (endoplasmic reticulum-Golgi intermediate compartment) of leaderless cargos (lacking the secretion signal sequence) such as the interleukin 1/IL-1; the translocation process is mediated by the cargo receptor TMED10. (Microbial infection) Binding to N.meningitidis NadA stimulates monocytes. Seems to interfere with N.meningitidis NadA-mediated invasion of human cells (Probable).
Synonyms: HSP84; HSP90B; HSPC2; HSPCB; D6S182
Tractability: Small molecule: a drug acting on it is in phase 2 or 3 trials; a structure with a bound ligand is known; a high-quality ligand is known; it has a high-quality binding pocket; it belongs to a druggable protein family. Antibody: UniProt places it where antibodies can reach, with high confidence; its Gene Ontology location is reachable by antibodies, with high confidence; the Human Protein Atlas places it where antibodies can reach. PROTAC: UniProt records ubiquitination sites on it; ubiquitination databases record sites on it; its protein half-life has been measured; a small molecule that binds it is known. Other modalities: a drug acting on it is in phase 2 or 3 trials.
Target class: Other cytosolic protein
Chemical probes: BIIB021 (high quality), ONALESPIB (high quality), PD080718, PD081903, PD082560, PD082995, PD083616, PD083648, PD084477, PD084746, PD134552, PD134553, PD134554, luminespib (high quality)
Safety:
Unwanted effects reported when the protein is acted on. In parentheses: how it was acted on, where the effect was seen, and who reports it.
hypertension (source: ClinPGx)
Gene: Protein-coding gene on chromosome 6 (44,245,808 to 44,253,888, forward strand). Ensembl gene ENSG00000096384.
Subcellular location: Cytoplasm; Melanosome; Nucleus; Secreted; Cell membrane; Dynein axonemal particle; Cell surface
Subcellular location (Human Protein Atlas): Plasma membrane; Cytosol
Pathways (Reactome):
Disease: Assembly and release of respiratory syncytial virus (RSV) virions; Dengue virus activates/modulates innate and adaptive immune responses; Potential therapeutics for SARS; Purinergic signaling in leishmaniasis infection; Respiratory syncytial virus genome replication; SARS-CoV-2 activates/modulates innate and adaptive immune responses; Uptake and function of diphtheria toxin
Cellular responses to stimuli: Attenuation phase; HSF1 activation; HSF1-dependent transactivation; HSP90 chaperone cycle for steroid hormone receptors (SHR) in the presence of ligand
Immune System: DDX58/IFIH1-mediated induction of interferon-alpha/beta; Neutrophil degranulation; Regulation of actin dynamics for phagocytic cup formation; The NLRP3 inflammasome
Signal Transduction: ESR-mediated signaling; Estrogen-dependent gene expression; RHOBTB2 GTPase cycle
Autophagy: Chaperone Mediated Autophagy
Cell Cycle: The role of GTSE1 in G2/M progression after G2 checkpoint
Developmental Biology: Sema3A PAK dependent Axon repulsion
Metabolism: Aryl hydrocarbon receptor signalling
Gene Ontology:
Molecular function: ATP binding; ATP-dependent protein binding; cadherin binding; disordered domain specific binding; DNA polymerase binding; double-stranded RNA binding; heat shock protein binding; histone deacetylase binding; histone methyltransferase binding; identical protein binding; kinase binding; MHC class II protein complex binding; peptide binding; protein binding; protein dimerization activity; protein homodimerization activity; protein phosphatase activator activity; receptor ligand inhibitor activity; RNA binding; ubiquitin protein ligase binding; ATP hydrolysis activity; nitric-oxide synthase regulator activity; protein folding chaperone; tau protein binding; TPR domain binding; and 3 more
Biological process: chaperone-mediated protein complex assembly; negative regulation of proteasomal ubiquitin-dependent protein catabolic process; positive regulation of cell differentiation; positive regulation of protein localization to cell surface; positive regulation of transforming growth factor beta receptor signaling pathway; regulation of cell cycle; regulation of protein ubiquitination; supramolecular fiber organization; telomerase holoenzyme complex assembly; telomere maintenance via telomerase; virion attachment to host cell; cellular response to heat; negative regulation of proteasomal protein catabolic process; positive regulation of nitric oxide biosynthetic process; protein folding; regulation of protein localization; response to unfolded protein
Cellular component: aryl hydrocarbon receptor complex; cell surface; COP9 signalosome; cytoplasm; cytosol; extracellular exosome; extracellular region; HSP90-CDC37 chaperone complex; melanosome; membrane; mitochondrion; nucleus; plasma membrane; protein folding chaperone complex; protein-containing complex; axonal growth cone; dendritic growth cone; dynein axonemal particle; ficolin-1-rich granule lumen; neuronal cell body; nucleoplasm; perinuclear region of cytoplasm; secretory granule lumen
Genetic constraint (gnomAD): Loss-of-function variants: 16 observed, 69.45 expected, observed/expected ratio (o/e) 0.23, 90% interval 0.16 to 0.35. The synonymous counts are far from expectation, so gnomAD's model fits this gene poorly and the ratio says little. Missense variants: 687 observed, 917.62 expected, observed/expected ratio (o/e) 0.75, 90% interval 0.7 to 0.8. Synonymous variants: 387 observed, 316.26 expected, observed/expected ratio (o/e) 1.22, 90% interval 1.12 to 1.33.
Homologues: Orthologues: macaque HSP90AB1 (99% identical), mouse Hsp90ab1 (99% identical), pig HSP90AB1 (99% identical), rat Hsp90ab1 (99% identical), guinea pig HSP90AB1 (99% identical), rabbit HSP90AB1 (99% identical), dog HSP90AB1 (97% identical), tropical clawed frog hsp90ab1 (93% identical), zebrafish hsp90ab1 (91% identical), Drosophila melanogaster Hsp83 (78% identical), Caenorhabditis elegans hsp-90 (75% identical). Paralogues in human: HSP90AA1 (87% identical), HSP90B1 (49% identical), TRAP1 (30% identical).
Diseases named in the same sentence as HSP90AB1 in open-access papers:
HSP90AB1 is named in the same sentence as 166 diseases in open-access papers, as found by Europe PMC text mining. Sharing a sentence is not in itself a finding about the gene and the disease. The quoted sentences say what the papers report.
breast cancer (45 papers, 2010 to 2025). A primary or metastatic malignant neoplasm involving the breast. "Analysis of TCGA data showed that high HSP90AB1 expression was also associated with poor prognosis in breast cancer but with a better prognosis in rectal cancer patients." (PMID 36035171, 2022). "Previously, Hsp90ab1 has been implicated to have an oncogenic role in laryngeal carcinoma, non-small-cell lung cancer, and breast cancer by promoting tumorigenesis." (PMID 30305727, 2019). "These include PTGS2, EGFR, ESR2, MMP2, JUN, and HSP90AB1, which all revealed the highest mRNA expression level in the basal breast cancer subtype, thus proposing a potential similar engagement of these genes in the pathogenesis of the basal subtype." (PMID 39707884, 2024). "Other typical HSF1 targets upregulated by heat shock (e.g., HSPA1A, HSPA1B, HSP90AB1) showed higher expression levels in all HSF1high breast cancers." (PMID 36010586, 2022). "The downregulation of HSP90AB1 was confirmed at the protein level in these cell lines as well as in colorectal and mammary tumors in mice with tissue-specific Usp22 deletions." (PMID 31801945, 2019). "RT-qPCR revealed that Hsp90AA1 and Hsp90AB1 mRNA levels increased in breast cancer, consistent with TCGA data." (PMID 31921692, 2019). "High-level expression of HSP90AB1 was an independent factor affecting disease-specific survival (death from breast cancer) and over-all survival of breast cancer." (PMID 22510516, 2012). "Besides, HSP90AB1 plays an important role in promoting tumor progression in melanoma, breast cancer, gastric cancer, and head and neck squamous cell carcinoma." (PMID 38327651, 2023). "HSP90AB1, a target gene of USP22, is associated with poor prognosis in breast cancer." (PMID 35935969, 2022). "We identified HSP90AB1 as the only up-regulated protein hub common to all cell types in our study, which highlights the fact that the cancer subtypes addressed here all share a core of proliferative signaling pathways common in breast cancers, but with many specificities." (PMID 25625699, 2015). "The sub-localization of HSP90AA1 and HSP90AB1 in human cells certified that HSP90AA1 and HSP90AB1 proteins resided in the cytosol based on the evidence provided by 62 types of breast cancer cell lines, including MCF-7 and MDA-MB-231." (PMID 40076902, 2025). "In breast cancer, the Top 5 genes were MYC, EGFR, SRC, HSP90AB1, PXDNL, and the Top 4 genes are CGC drivers." (PMID 40478912, 2025). "Several known proteins (including HSP90AB1, HSPB1, LDHA, ENO1, PGK1, KRT18, and AKR1C2) and pathways were observed between model breast cancer cell lines related to hormone response, cell metabolism, and cell morphology." (PMID 36937585, 2023). "Highly expressed HSP90AB1 and HSP90B1 negatively correlated with the infiltration of CD4+ T cells in a study exploring immune infiltration in breast cancer." (PMID 38259468, 2023). "In response to the application of recombinant Hsp90ab1 and MSN, we observed a reduction in the EdU-based proliferation and transwell invasion of EO771 mammary tumor cells." (PMID 34976221, 2022). "In this study, we investigated the expression patterns and prognostic values of different HSP90 family members (HSP90AA1, HSP90AA2, HSP90AB1, HSP90B1, and TRAP1) in breast cancer." (PMID 34109171, 2021). "In summary, our results indicated that although gene expression levels of HSP90AA1, HSP90AA2, HSP90AB1, HSP90B1, and TRAP1 were upregulated in breast cancer patients, only the expression of HSP90AA1 was related to the tumor stage and prognostic survival." (PMID 34109171, 2021). "Although the mRNA levels of HSP90AB1, HSP90B1, and TRAP1 were increased in breast cancer tissues compared with those in normal tissues, the mRNA levels were not significant." (PMID 34109171, 2021).
breast cancer (continued). "Based on the results of the present study, we suggest the use of HSP90AB1, DAD1, PFN1 and PUM1 in any combination of threes (triplet) for normalization of the expression of genes of interest in SK-BR-3 breast cancer cell line." (PMID 34681026, 2021). "Multiple heat shock proteins, including Hsp90AA1, Hsp90AB1, TRAP1, HspA5, HspB1, HspE1, HspD1, HspA1B, HspA8, HspA9, and HspA4, were significantly upregulated in breast cancer tissue." (PMID 31921692, 2019). "Hsp90AA1, Hsp90AB1, TRAP1, HspA5, HspB1, HspE1, HspD1, HspA1B, HspA8, HspA9, and HspA4 were validated as potential biomarkers for breast cancer tissue." (PMID 31921692, 2019). "Heat shock proteins showed the most significant change of all the upregulated domains, with Hsp90AA1, Hsp90AB1, TRAP1, HspA5, HspB1, HspE1, HspD1, HspA1B, HspA8, HspA9, and HspA4 identified in breast cancer tissue." (PMID 31921692, 2019). "Previously, using systems biology approach and cancer signaling networks, we identified top-5 highly expressed and connected proteins (HSP90AB1, CSNK2B, TK1, YWHAB and VIM) in the invasive MDA-MB-231 breast cancer cell line." (PMID 27527857, 2016). "We found that HSP90AA1 and HSP90AB1, two cytoplasmic HSP90 isoforms, were among the most significant factors of poor prognosis in different breast cancer subtypes." (PMID 22510516, 2012). "Importantly, we found both cytoplasmic HSP90 isoforms, HSP90AA1 and HSP90AB1, were among the most significant factors that led to higher risk of death from breast cancer, indicating that HSP90 plays an important role in modulating poor prognosis phenotypes in breast cancer." (PMID 22510516, 2012). "Transcript levels of five of the seven metabolic genes (TALDO1, GPI, SHMT2, LDHA, and ADK: 5-gene metabolic signature) and six oncogenes: TAGLN2, NOLC1, HSP90AB1, HDGF, MCM5, and NCL, were elevated in TNBC patients when compared to patients with ER+ breast cancer." (PMID 34711841, 2021). "All six thermogenes appear to be significantly overexpressed in breast cancer (HSPA1A, HSPA4), gliomas (DNAJB5), ovarian cancers (HSPA4, DNAJB5), pancreatic cancers (HSP90AA1), prostate cancer (HSP90AB1), thymic carcinoma (BAG1, HSP90AA1), and uterine cancers (HSPA4), as compared to normal tissue." (PMID 31814876, 2019). "Interestingly, we identified outlier phosphosites in genes not previously implicated in breast cancer through genomic profiles, such as BRAF p.S447, p.S750 and HSP90AB1 p.Y56 and p.S169." (PMID 28348404, 2017). "Furthermore, amplification of HSF1 was correlated with higher HSP90AA1 and HSP90AB1 mRNA expression among the breast cancer cells without amplifications of these two genes." (PMID 22510516, 2012).
lung carcinoma (17 papers, 2012 to 2025). "An increasing number of previous studies have demonstrated that upregulation of HSP90AB1 abundance can promote the invasion and metastasis of various cancers, such as gastric cancer, lung cancer, and colon cancer." (PMID 37587463, 2023). "HSP90AB1 contributes to pathogenesis and progression of lung cancer, hepatocellular carcinoma, laryngeal carcinoma." (PMID 31949199, 2020). "It is also reported that Hsp90ab1 overexpression promotes the angiogenesis, metastasis and differentiation of hepatocellular carcinomas and lung cancer." (PMID 30305727, 2019). "Hsp90AB1 protein was over-expressed in NSCLC tissues, and was associated with lung cancer pathological type and overall survival in lung adenocarcinoma patients." (PMID 26903158, 2016). "The expression level of Hsp90AB1 in lung cancer tissues (positive rate of 54.0%) was significantly higher than that in normal lung tissue (positive rate of 0.0%, P < 0.001)." (PMID 26903158, 2016). "On the basis of these observations, our findings on Ephexin1’s regulation of 5′-TOP mRNA translation, we hypothesized that mTOR target genes, such as HSP90ab1, eEF1a1 and c-Myc, along with Ephexin1, are involved in lung cancer progression." (PMID 40855114, 2025). "For example, Cortex Lycii may inhibit epithelial–mesenchymal transition (EMT) in lung cancer cells by targeting HSP90AB1." (PMID 41209079, 2025). "Other studies also have shown that HSP90AB1 was upregulated in lung cancer and melanoma tumor." (PMID 27756247, 2016). "HSP90AB1 and its related homology HSP90AA1 have important potential in the treatment of lung cancer." (PMID 39859536, 2025). "For instance, we identified three heat shock protein (HSP) genes, HSP 90 alpha family class B member 1 (HSP90AB1), HSP family A member 8 (HSPA8), and HSP family A member 5 (HSPA5), as novel biomarkers in lung cancer and GBM." (PMID 33277589, 2020).
gastric cancer (14 papers, 2009 to 2025). A primary or metastatic malignant neoplasm involving the stomach. "HSP90AB1 is a molecular chaperone with roles in tumorigenesis that activates the Wnt/β-catenin signaling pathway in gastric cancer that also enhances the TGF-β/SMAD signaling in lung adenocarcinoma (LUAD), promoting EMT in both scenarios." (PMID 35500936, 2022). "Previous studies have demonstrated that Hsp90ab1 binds LRP5 to activate AKT and Wnt/β-catenin signaling, promoting invasion and metastasis in gastric cancer cells." (PMID 40713830, 2025). "The stage-based assessment of overexpressed genes showed significant upregulation of CST1, INHBA, ACAN, HSP90AB1, and HSPD1 genes across all stages, including early, locally advanced and metastatic stomach cancer." (PMID 33828156, 2021). "Our analysis showed that compared with normal stomach tissue, CST1, INHBA, ACAN, HSP90AB1, and HSPD1 were the leading five genes that were overexpressed in stomach cancer." (PMID 33828156, 2021). "Comparison between normal stomach tissue and stomach tumors showed that CST1 (p = 3.97E−21), INHBA (p = 9.22E−20), ACAN (p = 1.08E−19), HSP90AB1 (p = 2.62E−19), and HSPD1 (p = 3.91E−19) were the leading five genes that were overexpressed in stomach cancer." (PMID 33828156, 2021). "The hub proteins identified, CAT, PLEKHA4, HSP90AB1, TXN, EEF2, H6PD, and PDIA3, may play important roles in the treatment of gastric cancer using nintedanib." (PMID 38406279, 2024).
colon carcinoma (12 papers, 2016 to 2023). "Only HSP90AB1, RIPK2, DDX21, UCHL5, GTPBP4, and PCID2 were significantly different in UC and COAD tissues, and they all showed overexpression in colon cancer tissues compared to UC tissues." (PMID 35372018, 2022). "On the other hand, the expression of Hsp90aa1 and Hsp90ab1 increased in colon cancer cells, regardless of the cancer grade, compared to that in normal colon fibroblast cells (CCD18Co)." (PMID 34620942, 2021).
leukemia (10 papers, 2012 to 2025). A malignant (clonal) hematologic disorder, involving hematopoietic stem cells and characterized by the presence of primitive or atypical myeloid or lymphoid cells in the bone marrow and the blood. "Three genes activated by v-Abl caught our attention due to their involvement in leukemia and cancer: Hmga1 (NM_016660), hnRNP A1 (NM_010447), and Hsp90ab1." (PMID 22693568, 2012). "Likewise, Hsp90ab1 has also been shown to promote leukemia cell proliferation by preventing the auto-ubiquitination and degradation of c-IAP1, a member of the inhibitor of apoptosis protein (IAP) family." (PMID 30305727, 2019). "However, the role of HSP90AB1 in the pathogenesis of leukemia is rarely reported." (PMID 34217296, 2021).